CBS (cystathionine beta-synthase)
Diseases named in the same sentence as CBS in open-access papers (continued):
Sharing a sentence is not in itself a finding about the gene and the disease.
colon cancer (continued). "It has been recently demonstrated that CBS is abundantly expressed in human colon cancer cell lines and in human colon cancer tissue specimens, resulting in increased H2S production." (PMID 27385096, 2016). "Recently, CBS has emerged as a potential therapeutic target in both colon cancer and ovarian cancer." (PMID 27461275, 2016). "Colonic cancer cells have been shown to exhibit up-regulated expression of CBS and increased formation of H2S, which directs cell proliferation and angiogenesis in colon cancer." (PMID 25248148, 2014). "Through a series of studies involving the knocking in/out of CBS expression or CBS activity (allosteric activation via SAM or inhibition using amino-oxyacetic acid (AOAA) in the HCT116 colon cancer cell line, it was validated that CBS encourages tumor cell advancement." (PMID 38250807, 2024). "A study found that DNA methylation of the CBS promoter favors colon cancer progression." (PMID 37627515, 2023). "SAM can allosterically activate the CBS gene to favor the cell proliferation of colon cancer cells." (PMID 37627515, 2023). "The results showed that VEGF was down-regulated, blood vessel growth was blocked, and colon cancer liver metastasis was inhibited, suggesting that CBS could be used as a therapeutic target for colon cancer liver metastasis." (PMID 37020597, 2023). "CNNM4 is a member of the cyclin and cystathionine β-synthase (CBS) domain divalent metal cation transport mediator family and promotes tumor progression by regulating Mg2+ efflux; its level is inversely correlated with malignancy in colon cancer." (PMID 35486664, 2022). "We hypothesized that overexpression of cystathionine-beta-synthase (CBS)/H2S exerts an inhibitory effect on colon cancer cell proliferation and metastasis." (PMID 35172821, 2022). "Similarly, promising results were achieved by inhibiting the CBS, a significant contributor to H2S synthesis out of three essential enzymes; its expression heals cancer by reversing acquired resistance to 5-FU in colon cancer cell lines." (PMID 35684331, 2022). "Furthermore, CD44 and the transcription factor SP-1 was probably involved in the inhibitory effect of CBS/H2S axis on colon cancer cells." (PMID 35172821, 2022). "In addition, CBS has been reported to be overexpressed in ovarian, breast and colon cancer cells, where it contributes to cancer progression and drug resistance through its role in H2S synthesis." (PMID 35743210, 2022). "The activity of CBS could be allosterically elevated by S-adenosylmethionine (SAM), a universal methyl donor, which stabilizes CBS, to promote cell proliferation in colon cancer cells." (PMID 34207284, 2021). "Several malignant colon cancer-derived cell lines similarly showed high CBS expression." (PMID 35366284, 2021). "Similarly, we have noticed that several human colon cancer cell lines have highly expressed CBS levels." (PMID 33499368, 2021). "Increased expression of CBS has been revealed in colorectal cancer tissues and increased tumor-derived H2S has been validated to stimulate bioenergetics, cell proliferation, and angiogenesis in colon cancer." (PMID 32194794, 2020). "Increased expression of cystathionine β-synthase (CBS) and H2S in colon cancer tissue samples has been validated and tumor-derived H2S, mainly produced by CBS, stimulates bioenergetics, cell proliferation, and angiogenesis in colon cancer." (PMID 32194794, 2020). "Moreover, we also demonstrated that the loss of uL3 and the consequent upregulation of the cystathionine β synthase (CBS) enzyme correlated with ineffectiveness of 5-FU in lung and colon cancer cell lines." (PMID 28273808, 2017).
colon cancer (continued). "Additionally, benserazide could inhibit the proliferation of colon cancer cell line HT29 with high CBS expression, as well as the growth of tumors in nude mice carrying human colon cancer cell xenografts." (PMID 40442106, 2025). "Also, silencing or inhibition of CBS suppressed cellular bioenergetics of the colon cancer cells." (PMID 27808278, 2016). "Benserazide inhibited colon cancer cell proliferation in HCT116 and HT29 cell lines, both highly expressing CBS, impaired cellular bioenergetics in HCT116 cells and suppressed colon cancer tumor growth in mice." (PMID 40941984, 2025). "A synergistic effect has been observed between aminooxyacetic acid (AOAA), an inhibitor of CBS and CTH34, with sulfasalazine and erastin in colon cancer cells." (PMID 37381723, 2023). "Another study indicates that shRNA-mediated downregulation of CBS inhibits the proliferative, migrative, and invasive activities of HCT116 colon cancer cells in vitro and suppresses colon cancer growth and tumor angiogenesis in vivo." (PMID 35795862, 2022). "It is predicted that colon cancer patients’ serum homogenates and cell lines produce significantly more H2S suppressed by AOAA, a prototypical CBS inhibitor." (PMID 35684331, 2022). "CBS and other CSE cell lines develop H2S in larger amounts than other colon cancer cell lines, which is consistent with the conclusion that H2S promotes cell proliferation." (PMID 35684331, 2022). "We have also synthesized and tested derivatives of the prototypical CBS inhibitor aminooxyacetate (AOAA) in different cellular and animal models of colon cancer." (PMID 34439739, 2021). "In conclusion, this study demonstrates that CBS is overexpressed in human colorectal cancer and AOAA sensitizes colon cancer cells to OXA via increasing apoptosis both in vitro and in vivo." (PMID 32194794, 2020). "Our previous studies have shown that H2S was endogenously produced in a colon cancer cell line (WiDr) and colon tissues through the activities of both CSE and CBS." (PMID 26078811, 2015). "For example, in one study, CBS overexpression in the NCM356 colonic epithelial cell line induced broad changes in the transcriptome, with over 350 differentially expressed genes related to glycolysis, hypoxia, and colon cancer cell phenotypes." (PMID 40187942, 2025). "Another study indicates that CBS is overexpressed in colorectal cancer tissues, and AOAA could sensitize colon cancer cells to oxaliplatin by increasing intrinsic apoptosis." (PMID 35795862, 2022). "In 2013, a study comparing human colon cancer specimens with healthy mucosa tissue presented selective up-regulation of CBS in cancer tissue, whereas low CBS expression levels were observed in non-cancerous peri-tumor tissue." (PMID 35684331, 2022). "In order to extend our findings to other colon cancer cells, we have also tested the effect of the 3-MST inhibitor on HT-29 and LoVo cells, two additional human colon cancer cell lines which are known to produce H2S from CBS and 3-MST." (PMID 36113340, 2022). "The colon cancer-derived epithelial cell line HCT116 exhibits upregulation of CBS and increased H2S production compared to non-cancerous colon cells." (PMID 33330130, 2020). "Though expression of CBS has been recently reported to promote tumorigenesis in ovarian and colon cancer, with minimal to no expression in OSE cells, the role of CBS was never been elucidated in altered lipid metabolism of cancer cells so far." (PMID 26452259, 2015). "For example, it has been shown that APC down-regulation in CBS and Moser colon cancer cells converts the negative effect of TGFβ on wnt signalling into a positive one, without altering the amount of nuclear β-catenin." (PMID 22509309, 2012). "Also Szabo group highlighted that CBS is selectively upregulated in colon cancer tissues compared with non-malignant colonic epithelial tissues." (PMID 38250807, 2024).
colon cancer (continued). "Additionally, several human colon cancer cells displayed elevated CBS expression in comparison to normal non-malignant colon cancer cell lines (NCM356)." (PMID 38250807, 2024). "Colon cancer cells produced significant levels of lanthionine, a rare metabolic intermediate of CBS-mediated H2S biosynthesis; forced expression of CBS into non-transformed epithelial cells increased lanthionine biogenesis in vitro and in vivo (measured in the urine of tumor-bearing mice)." (PMID 34439739, 2021). "However, the effect of inhibition of the CBS/H2S axis on the sensitivity of colon cancer cells to OXA has not been illustrated." (PMID 32194794, 2020). "With a bioactive and selective inhibitor of CBS in hand, we examined the effect of CH004 on the proliferation of HepG2 and HEK293T cells as well as hepatocellular carcinoma Huh7 and H22, pancreatic cancer Panc-28, colon cancer HCT116 and breast cancer MDA-MB-231 cells." (PMID 30258181, 2018). "In this respect, EO771 cells appear to resemble the CT26 murine colon cancer cell line, in which also 3-MST (rather than CBS or CSE) appears to play the primary tumor-cell-supporting role." (PMID 36978895, 2023). "Unlike CBS, suppressing CSE (whose expression was intact in colon cancer) did not affect tumor development or bioenergetics." (PMID 35684331, 2022). "CBS knockdown or pharmacologic inhibition by aminooxyacetic acid (AOAA) reduced cell proliferation and H2S synthesis in the HCT116 colon cancer cell line, but not in the slower-growing nonmalignant NCM356 cell line." (PMID 35366284, 2021). "Indeed, more than decade ago, literature showed that, CBS not CSE, is responsible for colon cancer progression." (PMID 39643979, 2024).
ovarian carcinoma (46 papers, 2013 to 2025). A malignant neoplasm originating from the surface ovarian epithelium. "After examining 200 primary epithelial ovarian cancer patients’ tissues using microarrays, Bhattacharyya and colleagues found high levels of CBS expression, predominantly in a common histological variant of serous carcinoma." (PMID 35684331, 2022). "CBS encodes a homotetrameric enzyme that catalyzes the first step in the transsulfuration pathway and converses the homocysteine to cystathionine, which is associated with various stomach, liver, and ovarian cancers and influences immune evasion." (PMID 36313783, 2022). "Moreover, endogenous overexpression of CBS and the resulting increased H2S production in ovarian cancer cell lines are associated with metabolic reprogramming, mitochondrial morphogenesis, and chemoresistance." (PMID 31635026, 2019). "The majority of ovarian cancer cells showed high CBS expression (both on the mRNA and protein levels) compared to normal ovarian surface epithelial cells." (PMID 38250807, 2024). "In the same study, the authors also studied the regulatory role of CBS-derived H2S in modulating ovarian cancer cell proliferation, migration, and invasion in vitro and in vivo." (PMID 38250807, 2024). "Overexpression of CBS led to ferroptosis resistance in erastin-treated ovarian cancer cells, while depletion of CBS sensitized ferroptosis-resistant cells." (PMID 38908072, 2024). "CBS silencing inhibits tumor growth and neointimal density in rat models of colon and ovarian cancer, and low concentrations or endogenous H2S can promote tumor growth by promoting angiogenesis." (PMID 38448410, 2024). "In colon and ovarian cancers, CBS knockdown reduces the metastatic potential of cancer cells and decreases the number of sprouted blood vessels, thus resulting in the attenuation of tumor growth." (PMID 38250807, 2024). "In ovarian cancer cells, CBS regulates bioenergetics by regulating mitochondrial ROS production, oxygen consumption, and ATP generation." (PMID 37483514, 2023). "Our previous studies on ovarian cancer showed that selenium–chrysin (SeChry) anticancer effects were related to cysteine metabolic disruption due to CBS inhibition and GSH depletion." (PMID 38247476, 2023). "Meanwhile, down‐regulation of CBS enhances ovarian cancer sensitivity to cisplatin both in vivo and in vitro." (PMID 36929586, 2023). "In BJ-TERT and human mammary epithelial cells (HMEC), overexpressing AKT1E17K, a clinically relevant activated mutant form of AKT1 in multiple cancer types including breast cancer and ovarian cancer, also enhanced CBS protein expression." (PMID 35758651, 2022). "Bhattacharyya and colleagues investigated the functional role of CBS-derived H2S in inhibiting the proliferation, migration, and invasion of ovarian cancer in vitro, using a combination of genetic and pharmacological approaches." (PMID 35684331, 2022). "Additional studies should be performed to clarify the role of CBS in the cisplatin resistance of ovarian cancer." (PMID 35008958, 2022). "The expression of CBS was significantly increased in protein and mRNA levels in ovarian cancer cells." (PMID 35684331, 2022). "Knockdown of CBS decreases bioenergetics, actions such as oxygen consumption and ATP production in colon and ovarian cancer cells." (PMID 36741694, 2022). "According to Bhattacharya and colleagues, CBS reduced oxygen consumption in mitochondria, and similar effects were observed when ovarian cancer cell lines were treated with a CBS, AOAA inhibitor." (PMID 35684331, 2022). "Primary epithelial ovarian cancer tissues and several ovarian cancer cell lines are over-expressed with CBS." (PMID 35684331, 2022). "Taken together, these data demonstrate a role of CBS in the maintenance and regulation of mitochondrial function in ovarian cancer." (PMID 35366284, 2021). "CBS also regulates bioenergetics and mitochondria of ovarian cancer cells by increasing oxygen consumption and ATP generation." (PMID 34603448, 2021).
ovarian carcinoma (continued). "After down-regulation of CBS in ovarian cancer cell line A2780, the content of GSH decreased, which aggravated the cascade of apoptosis triggered by oxidative stress and enhanced the sensitivity to cisplatin." (PMID 34335475, 2021). "The first study, investigating the role of endogenous CBS on the organization of mitochondria in a cancer cell was conducted in ovarian cancer cells by Bhattacharyya and colleagues in a human ovarian cancer cell line (OvCa)." (PMID 33499368, 2021). "Lastly, siRNA CBS KD also increased the sensitivity of the ovarian cancer cell line to cisplatin, lowering the IC50 from 13.1 to 7.9 μM." (PMID 35366284, 2021). "CBS siRNA knockdown or AOAA treatment of the CBS-expressing ovarian cancer cells lines resulted in a significant suppression of cell proliferation (measured by 3H-thymine incorporation) and a lowered viability." (PMID 35366284, 2021). "The effects of CBS expression on tumor growth were examined in a previously developed murine orthotopic model of ovarian cancer." (PMID 35366284, 2021). "NRF2 can upregulate cystathionine β-synthase (CBS) to confer resistance to erastin-induced ferroptosis in ovarian cancer cells, however inhibition of CBS can trigger ferroptosis in HCC." (PMID 33868986, 2021). "Instead of the fused and elongated mitochondria observed in ovarian cancer cells, CBS-silenced cells presented with fragmented mitochondria lacking network, associated with mitofusin-2 down-regulation." (PMID 32365821, 2020). "For instance, in ovarian cancer, CBS silencing enhanced the efficacy of cisplatin to suppress ovarian cancer xenograft growth, nodule formation and vascularization." (PMID 32365821, 2020). "Collectively, our data support SeChry@PUREG4-FA nanoparticles as a targeted strategy to improve ovarian cancer treatment, where GSH depletion and CBS inhibition underlie SeChry cytotoxicity." (PMID 31635026, 2019). "CBS inhibition was suggested as an appealing strategy to combat chemoresistance in ovarian cancer, and as a generally valid anti-cancer approach." (PMID 31635026, 2019). "Recent studies demonstrating that CBS promotes colon and ovarian cancer growth in preclinical models highlight a newly identified oncogenic role for CBS." (PMID 30050925, 2018). "Bhattacharyya S, Saha S, Giri K. Cystathionine beta-synthase (CBS) contributes to advanced ovarian cancer progression and drug resistance." (PMID 27461275, 2016). "Strikingly, CBS localizes in mice ovaries and is responsible for follicular development suggesting the rationale of CBS involvement in ovarian cancer progression, as developmental pathways are reactivated in tumorigenesis." (PMID 26452259, 2015). "To provide further evidence for a role of CBS in ovarian cancer pathophysiology, we next investigated a role of CBS in ovarian cancer cell migration and invasion." (PMID 26452259, 2015). "Taken together the results indicate that CBS regulates lipid metabolism in ovarian cancer cells via regulation of SREBP expression, translocation and transcriptional activity." (PMID 26452259, 2015). "Taken together these results propose that CBS regulates lipid metabolism in ovarian cancer and provides a novel axis for ovarian cancer progression." (PMID 26452259, 2015). "Taken together our in vivo results indicate a potential role of CBS and SREBPs, in aberrant lipogenesis in ovarian cancer that promotes tumor growth." (PMID 26452259, 2015). "The present study reveals a novel molecular mechanism by which CBS promotes ovarian cancer growth and maintenance by involving SREBPs." (PMID 26452259, 2015). "We transiently silenced ovarian cancer cell lines with siRNA of CBS and compared with scrambled controls." (PMID 26452259, 2015). "Having confirmed that CBS and SREBPs are differentially overexpressed in ovarian cancer cell lines and possess significant lipid storage, we next sought to examine the functional significance and the correlation of CBS and SREBPs in ovarian cancer." (PMID 26452259, 2015).